LINC00528 (long independently transcribed non-coding RNA 528)
Synonyms: C22orf37; FLJ40542
Gene: Long non-coding RNA gene on chromosome 22 (17,777,317 to 17,780,519, forward strand). Ensembl gene ENSG00000269220.
Diseases named in the same sentence as LINC00528 in open-access papers:
LINC00528 is named in the same sentence as 15 diseases in open-access papers, as found by Europe PMC text mining. Sharing a sentence is not in itself a finding about the gene and the disease. The quoted sentences say what the papers report.
myocardial infarction (4 papers, 2020 to 2022). Gross necrosis of the myocardium, as a result of interruption of the blood supply to the area, as in coronary thrombosis. "Recently, LINC00528 was identified to regulate myocardial infarction by targeting the miR-143-3p/COX-2 axis." (PMID 33083450, 2020). "In addition, in a study published in 2020, the authors describe the expression of LINC00528 in cell models of myocardial infarction and explore its roles." (PMID 34414854, 2021). "For example, LINC00936 and LINC00528 were recently predicted to interact with TLR2 and the Toll-like receptor signaling pathway in acute myocardial infarction." (PMID 35945487, 2022). "This study is aimed to explore the roles of LINC00528 in myocardial infarction (MI) progression." (PMID 31833800, 2020).
breast carcinoma (1 paper, 2021). "Based on the results of prognostic analysis and clinical characterization, we hypothesized that the low expression level of LINC00528 at the late stage is likely to be an important factor for the late metastasis of HER2-positive breast cancer." (PMID 34257572, 2021).
laryngeal squamous cell carcinoma (1 paper, 2020). A squamous cell carcinoma that arises from the larynx. "On the other hand, LINC00528 has recently been demonstrated to relate to laryngeal squamous cell carcinoma." (PMID 33318305, 2020).
tumor (5 papers, 2020 to 2024). "This suggests that LINC00528 is closely associated with tumor cell metastasis." (PMID 34257572, 2021). "The expression of LINC00528 was found to be significantly higher in tumor tissues from individuals with a smoking history when compared to non-smoking tissues or adjacent normal tissues." (PMID 38028627, 2023). "LINC00528, a gene that emerges as a key protecting player in tumor progression, has demonstrated its potential in impeding cancer development by inducing programmed cell death and restraining cellular proliferation under laboratory conditions." (PMID 38028627, 2023). "LINC00528 has been shown to be highly expressed in tumor tissues of patients with laryngeal squamous cell cancer and was related to the poor prognosis of patients." (PMID 35401751, 2022). "This suggests that smoking may have a role in upregulating the expression of LINC00528 in tumor tissues." (PMID 38028627, 2023). "The mRNA expression of seven PRAN genes (CCL14, CPA3, CX3CR1, IKZF3, KIF21B, LINC00528, and SLC16A4) exhibited noticeable difference between normal and tumor in NSCLC." (PMID 38728242, 2024). "The mRNA expression of seven PRAN genes (CCL14, CPA3, CX3CR1, IKZF3, KIF21B, LINC00528, and SLC16A4) showed significant differences between normal and tumor samples in the advanced NSCLC cohort." (PMID 38728242, 2024). "Interestingly, LINC00528 was found to be expressed at higher levels in smoking patients with LSCC, but it seems did not affect the prognosis or tumor progression between smoking and non-smoking patients." (PMID 38028627, 2023).
cancer (3 papers, 2020 to 2023). A tumor composed of atypical neoplastic, often pleomorphic cells that invade other tissues. "Survival analysis based on GEPIA also showed that LINC00528 had a good prognostic value in various tumors (p < 0.05), which suggested that LINC00528 could play an important role in the mechanism of cancer metastasis." (PMID 34257572, 2021). "The intersection set of the two gene lists includes 5 lncRNAs (EIF1AX-AS1, LINC00115, LINC01237, MALAT1 and LINC00528), among which only LINC00115 and MALAT1 have been experimentally validated to correlate with cancers according to the lncRNADisease2.0 database." (PMID 33318305, 2020).
LINC00528 also shares sentences with these, for which no sentence is quoted: acute myeloid leukemia (1 paper); acute myocardial infarction (1); breast invasive carcinoma (1); cervical squamous cell carcinoma (1); endocervical adenocarcinoma (1); head and neck squamous cell carcinoma (1); lung adenocarcinoma (1); skin cutaneous melanoma (1); stomach adenocarcinoma (1); uveal melanoma (1).